ECEL1P2 (endothelin converting enzyme like 1 pseudogene 2)
Synonyms: ECEL2
Gene: Transcribed unprocessed pseudogene on chromosome 2 (232,386,701 to 232,387,457, reverse strand). Ensembl gene ENSG00000244280.
Diseases named in the same sentence as ECEL1P2 in open-access papers:
ECEL1P2 is named in the same sentence as 2 diseases in open-access papers, as found by Europe PMC text mining. Sharing a sentence is not in itself a finding about the gene and the disease.
ECEL1P2 shares sentences with these, for which no sentence is quoted: chronic obstructive pulmonary disease (1 paper); lung carcinoma (1).